ADH1C (alcohol dehydrogenase 1C (class I), gamma polypeptide)
Diseases named in the same sentence as ADH1C in open-access papers (continued):
Sharing a sentence is not in itself a finding about the gene and the disease.
hepatocellular carcinoma (4 papers, 2012 to 2026). A malignant tumor that arises from hepatocytes. "Alcohol dehydrogenase, ADH1C and ADH1B, are members of the alcohol dehydrogenase family and are associated with many cancers, especially hepatocellular carcinomas." (PMID 41374967, 2025).
Cirrhosis (3 papers, 2017 to 2023). A chronic disorder of the liver in which liver tissue becomes scarred and is partially replaced by regenerative nodules and fibrotic tissue resulting in loss of liver function. "A total of 97 HCC patients with cirrhosis were selected from TCGA, and 5 genes (ADH1C, ACSL4, GPD2, ME1, NCAPH2) were selected to construct a FAM-related prognosis signature via Lasso–Cox regression using this cohort." (PMID 36671526, 2023). "In addition, we choose ADH1C, one of the FAM-related prognostic signatures, as a typical example to validate its function in HCC development with in vitro experiments, as well as to explore the potential mechanisms underlying abnormal FA metabolism in the process from cirrhosis to HCC." (PMID 36671526, 2023). "Therefore, it cannot be ruled out that the association of the ADH1C rs283413 SNV with the risk of developing cirrhosis might actually be due to such a linkage." (PMID 34068303, 2021).
esophageal cancer (3 papers, 2021 to 2022). A primary or metastatic malignant neoplasm involving the esophagus. "This study focuses on analyzing associations between SNPs of essential enzymes for alcohol metabolism ADH1B, ADH1C, and ALDH2 and survival in esophageal cancer patients receiving postoperative radiotherapy." (PMID 36212135, 2022).
head and neck cancer (3 papers, 2021 to 2023). A primary or metastatic malignant neoplasm affecting the head and neck. "A previous study indicated that patients with positive ADH1C have an increased risk of head and neck cancer." (PMID 37077811, 2023).
myocardial infarction (3 papers, 2006 to 2026). Gross necrosis of the myocardium, as a result of interruption of the blood supply to the area, as in coronary thrombosis. "In another study, moderate drinkers who are homozygous for the slow-oxidizing ADH1C*2 allele, and therefore who are expected to drink at higher levels than those with the ADH1C*1 allele, showed a substantially decreased risk of heart attack (i.e., myocardial infarction)." (PMID 17718403, 2006). "In line with the hypothesis that ethanol is largely responsible for the inverse association between alcohol consumption and coronary events, individuals with the slow ADH1C*2/2 genotype had a lower risk of myocardial infarction (MI) in a study among male physicians." (PMID 22363810, 2012).
oral cancer (3 papers, 2020 to 2023). "The polymorphism of ADH1C may be a crucial factor in the etiology of oral cancer and genetically determine an individual’s susceptibility." (PMID 37077811, 2023). "ADH1C is associated with susceptibility to oral cancer, and may have anti-oncogenic, proapoptotic effects." (PMID 32631357, 2020).
pancreatic cancer (3 papers, 2011 to 2024). "We established and validated a prognostic model for pancreatic cancer with 7 signatures, including ADH1C, APOE, RAP1GAP, NPC1L1, P4HB, SOD2, and TNFSF10." (PMID 38685045, 2024). "The role of ADH1C in pancreatic cancer is rarely reported and needs further study." (PMID 38685045, 2024).
coronary heart disease (2 papers, 2012 to 2024). "Additionally, we report results on associations of variants in ADH1B and ADH1C with ischemic heart disease and stroke in the context of a meta-analysis of previously published prospective studies published up to November 2011." (PMID 22363810, 2012).
diabetes (2 papers, 2019 to 2021). "After adjusted by age, sex, hypertension, diabetes mellitus, and alcohol, we found a significant interaction effect of AD–rs2241894 genotype on plasma ADH1C level (p = 0.04)." (PMID 33551739, 2021).
esophageal squamous cell carcinoma (2 papers, 2020 to 2022). Esophageal squamous cell carcinoma (ESCC) is a type of esophageal carcinoma (EC) that can affect any part of the esophagus, but is usually located in the upper or middle third. "Other researchers proved that the gene polymorphisms in ADH1C might change the risk of forming esophageal squamous cell carcinoma by regulating acetaldehyde metabolism and propensity to drink." (PMID 32903581, 2020).
Familial adenomatous polyposis (2 papers, 2021 to 2022). Familial adenomatous polyposis (FAP) is characterized by the development of hundreds to thousands of adenomas in the rectum and colon during the second decade of life. "CLCA1 and ADH1C were shown to be downregulated in familial adenomatous polyposis." (PMID 33648461, 2021).
glaucoma (2 papers, 2022 to 2025). Increased pressure in the eyeball due to obstruction of the outflow of aqueous humor. "In conclusion, our research shows that ENO2, NAMPT, and ADH1C can be used as diagnostic markers for glaucoma, and ENO2 can be used as a therapeutic target." (PMID 35366826, 2022). "Our research shows that ENO2, NAMPT, and ADH1C as diagnostic markers have been proved to be effective in the diagnosis of glaucoma, and ENO2 is a potential therapeutic target." (PMID 35366826, 2022). "The development of glaucoma is associated with oxidative stress, ADH1C may be related to oxidative stress and mitochondrial dysfunction in glaucoma." (PMID 35366826, 2022). "In our study, the glaucoma diagnosis model was constructed by machine learning algorithm LR-RF and LASSO algorithm, and 3 diagnostic biomarkers ADH1C, ENO2, and NAMPT were confirmed." (PMID 35366826, 2022). "Next, the expression analysis of the three diagnostic biomarkers in glaucoma and control samples confirmed that NAMPT and ADH1C were up-regulated in glaucoma samples, and ENO2 was down-regulated." (PMID 35366826, 2022). "The discovery of ADH1C may play a foundation for studying the pathogenesis of glaucoma from the aspects of oxidative emergency and antioxidation." (PMID 35366826, 2022). "The expression of 3 biomarkers in the GSE9944 dataset suggested that NAMPT and ADH1C were up-regulated and ENO2 down-regulated in glaucoma samples." (PMID 35366826, 2022). "NAMPT and ADH1C were up-regulated in glaucoma samples, contrary ENO2 was down-regulated in glaucoma samples." (PMID 35366826, 2022).
lung adenocarcinoma (2 papers, 2022 to 2024). A carcinoma that arises from the lung and is characterized by the presence of malignant glandular epithelial cells. "Feng’s study showed that the upregulated expression of ADH1C enhances cisplatin resistance of lung adenocarcinoma cells." (PMID 36212135, 2022).
non-small cell lung carcinoma (2 papers, 2021 to 2022). A group of at least three distinct histological types of lung cancer, including non-small cell squamous cell carcinoma, adenocarcinoma, and large cell carcinoma. "It has been confirmed that low expression of ADH1C is associated with poor prognosis in patients with non-small cell lung cancer." (PMID 35236335, 2022). "High expression of ADH1C was found to protect patients of non-small cell lung cancer." (PMID 34178026, 2021).
pharyngeal cancer (2 papers, 2012 to 2018). "In fact, it was reported that individuals homozygous for the ADH1C*1 allele, which consumed a high amount of alcohol, had a 5.3-fold increased risk of oral and pharyngeal cancer compared to ADH1C*1/2 and ADH1C*2/2 subjects." (PMID 29342885, 2018). "However, a similar meta-analysis reported recently had shown that ADH1C*1 allele was associated with a significantly decreased risk of pharynx cancer in dominant model." (PMID 22675424, 2012).
Stroke (2 papers, 2012 to 2024). Sudden impairment of blood flow to a part of the brain due to occlusion or rupture of an artery to the brain. "In comparison, individuals belonging to the highest consumption category and carrying the slow-metabolizing ADH1C*2/2 genotype were found to be at an increased risk of stroke." (PMID 22363810, 2012). "Probability values for interaction between ADH1C genotype and alcohol consumption were 0.097 for MI and 0.074 for stroke." (PMID 22363810, 2012). "Other studies provided little evidence for an association between ADH1C genotype and coronary events or stroke across strata of alcohol consumption and the same applies to the association between ADH1B genotype and acute coronary syndrome." (PMID 22363810, 2012).
type 2 diabetes (2 papers, 2022 to 2024). "In a previous study, an interaction between the ADH1C genotype and alcohol consumption was observed to influence the risk of type 2 diabetes among women." (PMID 35713687, 2022).
ulcerative colitis (2 papers, 2022 to 2023). An inflammatory bowel disease involving the mucosal surface of the large intestine and rectum. "The gene ADH1C might lead the increasing production of proinflammatory mediators by decreasing its expressions in the ulcerative colitis colon through the activation of the STAT1/NF-κB signaling pathway." (PMID 36991484, 2023).
alcoholic hepatitis (1 paper, 2024). Acute hepatitis resulting from ingestion of alcohol. "However, our analysis of the GSE28691 database showed that ADH1A and ADH1C were downregulated in liver tissues of patients with alcoholic hepatitis, while ADH1B and ADH5 showed no significant changes." (PMID 39044161, 2024).
Cognitive impairment (1 paper, 2021). Abnormal cognition is characterized by deficits in thinking, reasoning, or remembering. "We examined the associations of four single nucleotide polymorphisms (SNPs) on aldehyde dehydrogenase (ALDH) and alcohol dehydrogenase (ADH) genes (i.e., ALDH2 rs671, ADH1B rs1229984, ADH1B rs1042026, and ADH1C rs1693482) and cognitive impairment among the oldest-old." (PMID 35368830, 2021).
colorectal adenocarcinoma (1 paper, 2025). The most common type of colorectal carcinoma. "Potential diagnostic transcripts may include ADH1C, GGT5, NQO2, and SLC25A5 in colorectal adenocarcinoma." (PMID 41465541, 2025).
colorectal adenoma (1 paper, 2021). An adenoma that arises from the colon or rectum. "In summary, this study identified a set of differentially expressed genes in CRC, including FcGBP, CLCA1, ADH1C, COL1A1, ZG16, which could be strong candidates to be used as biomarkers of colorectal adenoma-adenocarcinoma progression." (PMID 33648461, 2021).
facial cleft (1 paper, 2022). A congenital abnormality consisting of an opening or gap in the face, which results from incomplete fusion of one or more of the embryonic facial prominences. "Since some studies believed that the occurrence of the facial cleft was related to some genes related to craniofacial malformation such as IRF6, ALX1, ALX3, and ADH1C." (PMID 36090555, 2022).
hippocampal atrophy (1 paper, 2025). "Similarly, ADH1 C’s involvement in retinol metabolism underscores the underappreciated role of retinoid signaling in dopaminergic neuron survival—a pathway corroborated by preclinical models showing retinoic acid deficiency exacerbates hippocampal atrophy." (PMID 40355913, 2025).
hyperlipidemia (1 paper, 2023). "V. dunalianum and 6'-O-caffeoyl-arbutin were found to regulate the expression of ADH1C protein and play a role in lowering blood lipids in the high-fat diet-induced rat model of hyperlipidemia." (PMID 37537524, 2023).
laryngeal squamous cell carcinoma (1 paper, 2020). A squamous cell carcinoma that arises from the larynx. "In a gene expression study on laryngeal squamous cell carcinoma, a subtype of HNSCC, ADH1C, and ADH7 showed a tumor stage-dependent decreasing expression pattern." (PMID 31940827, 2020).
nicotine addiction (1 paper, 2014). "We investigated six variants known to influence nicotine addiction or alcohol metabolism, including rs16969968 (CHRNA5), rs578776 (CHRNA3), rs1229984 (ADH1B), rs698 (ADH1C), rs1573496 (ADH7), and rs4767364 (ALDH2)." (PMID 24505444, 2014). "We found that the variants in alcohol dehydrogenase genes- rs1229984 (ADH1B), rs698 (ADH1C) and rs1573496 (ADH7) and the nicotine dependence gene variant rs16969968 were less common among Indians compared to previous studies in predominantly western populations." (PMID 24505444, 2014).
orofacial cleft (1 paper, 2020). A disorder of facial skeleton that is characterized by cleft lip and/or cleft palate that result in feeding, speech and hearing problems caused by failures during development. "For example, there is some evidence that the maternal and foetal ADH1C haplotype may modify the association between maternal alcohol consumption and risk of orofacial clefts via alcohol metabolism." (PMID 32710482, 2020).
ovarian carcinoma (1 paper, 2022). A malignant neoplasm originating from the surface ovarian epithelium. "The SNP rs698 in ADH1C significantly affects complete tumor response in ovarian cancer patients receiving cisplatin for chemotherapy." (PMID 36212135, 2022).
vitamin A deficiency (1 paper, 2024). Deficiency of vitamin A due to malnutrition, malabsorption, or dietary lack. "This study showed that ADH1C null mice produce less RA in vivo, resulting in growth failure and postnatal lethality, particularly under conditions of vitamin A deficiency." (PMID 38886650, 2024).
cancer (29 papers, 2011 to 2025). A tumor composed of atypical neoplastic, often pleomorphic cells that invade other tissues. "ADH polymorphisms correlate with cancer risk, and they encompass three gene loci (ADH1A, ADH1B, ADH1C) containing genetic variations that elevate cancer risk, particularly with heavy alcohol consumption." (PMID 41148854, 2025). "Epidemiological studies revealed that ADH1C alleles that lead to the accumulation of acetaldehyde in organisms can increase the risk of alcohol-derived cancers in the mammary gland." (PMID 36310188, 2023). "The ADH1C gene is critical in cancer development because it has two alleles, a highly active allele ADH1C*1 and the less active allele ADH1C*2." (PMID 36310188, 2023). "Studies on the effect of ADH1C polymorphisms on the risk of developing UADT cancers have shown contradictory results." (PMID 29342885, 2018). "Here, we performed a meta-analysis on 35 eligible case-control studies to estimate the overall cancer risk and ADH1C polymorphisms." (PMID 22675424, 2012). "To date, studies investigated the association between a functional polymorphism in ADH1C, Ile350Val (rs698), and risk of cancer have shown inclusive results." (PMID 22675424, 2012). "There were 35 studies retrieved on the basis of the search criteria for cancer susceptibility associated with ADH1C Ile350Val polymorphisms." (PMID 22675424, 2012). "Although many studies have investigated the association between the ADH1C polymorphism and cancer risk, the results were inconsistent." (PMID 22675424, 2012). "Based on the vital role of ADH1C in ethanol oxidation to AA, numerous studies have investigated the association of the functional ADH1C polymorphism with types of cancers." (PMID 22675424, 2012). "Several studies have observed significant association between ADH1C*1 allele and cancer risk." (PMID 22675424, 2012). "The results indicate that ADH1C Ile350Val polymorphism may contribute to cancer risk among Africans and Asians." (PMID 22675424, 2012). "Stratification analyses of the ADH1C Ile350Val polymorphism on cancer." (PMID 22675424, 2012). "Thus, the detail mechanism underlying ADH1C polymorphism and cancer risk remains controversial and the hypothesis that the variant of ADH1C exert an independent influence on cancer risk by changing ethanol oxidizing capacity was better founded." (PMID 22675424, 2012). "The results revealed that ADH1C expression is downregulated in several cancers including BC (P < 0.01)." (PMID 38173442, 2024). "Previous studies have highlighted ADH1C as an anti-cancer gene and its capability to curtail cell proliferation in CRC when overexpressed." (PMID 38308235, 2024). "Subgroup-specific genes with strong effects on overall survival and high MIFs in the proposed weighted model involve the following cancer-related genes: ADH1C, BMP5, LCN2 and PLOD2 in GSE31210, CST1 in GSE37745, as well as AREG and COL4A3 in GSE29013." (PMID 34876106, 2021). "Our results are consistent with a previous study that observed class I ADH (including ADH1A, ADH1B and ADH1C) to be more highly expressed, at both mRNA and protein levels, in normal breast tissues from cancer-free women than in invasive breast tumor tissues." (PMID 28899409, 2017). "SNPs in this region (i.e. rs1229984 [ADH1B], rs1789924 [ADH1C] and rs971074 [ADH7]) have previously been associated with overall UADT cancer." (PMID 22662130, 2012). "Odds ratio for cancer of the upper aerodigestive tract in heavy drinkers with ADH1C*2/*2 genotype was 7·1 (2·3-22·0) compared with 2·3 (1·4-3·8) for ADH1C homozygous wildtype (ie, *1) or heterozygous individuals." (PMID 21211041, 2011). "As a member of the ADH family, ADH1C is involved in the development of several cancers." (PMID 36671526, 2023). "Some studies have shown the correlation between SNPs of ADH1C and cancer prognosis." (PMID 36212135, 2022).
cancer (continued). "Finally, the mechanism of action of ADH1C in cancer has not been clearly understood, and more extensive and in-depth mechanism studies are needed to better understand the role of rs1789924 in ESCC." (PMID 36212135, 2022). "In conclusion, our results suggested that the ADH1C Ile350Val polymorphism is not a candidate for susceptibility to overall cancers." (PMID 22675424, 2012). "The study indicated that phase I transcripts, ADH1C and GGT5, phase II NQO2, and phase III SLC25A5 may have diagnostic and therapeutic potential in CRC due to their differential expression in the early phase of this cancer." (PMID 41465541, 2025). "Furthermore, there were also some studies suggesting that the influence of ADH1C polymorphism on cancer risk was independent of that of ADH1B in both European and Asian populations." (PMID 22675424, 2012). "The expression of TF-protein YY1 (a regulator of CXCL8, ADH1C, CEMIP, ZG16, and CLCA4) contributes to tumor growth differs in different cancers." (PMID 36991484, 2023). "The same authors also correlated the decreased expression of ADH1B and ADH1C with advanced stages of colorectal carcinomas, overall indicating that dysregulation of the ATRA biosynthesis can be responsible of the cancer progression." (PMID 32012980, 2020). "Alcohol dehydrogenase 1C (ADH1C) is the key enzyme catalyze oxidation of alcohol to acetaldehyde, which plays vital roles in the etiology of various cancer." (PMID 22675424, 2012). "Differential expressions in the initial stage of cancer (CSI or CSI and CSII), such as for ADH1C, GGT5, NQO2, and SLC25A5 (bolded), may indicate them as candidates for diagnostic biomarkers." (PMID 41465541, 2025). "ADH1C is a member of the ADH family that catalyzes the oxidation of ethyl alcohol to acetaldehyde (a carcinogenic metabolite) and plays a crucial role in the etiology of various cancers." (PMID 37077811, 2023). "Similarly, no report was available for the regulation of ADH1C mRNA in cancer, and it showed no integration into our network except a physical interaction with ADH1B." (PMID 28962550, 2017).